KMT2D (lysine methyltransferase 2D)
Diseases named in the same sentence as KMT2D in open-access papers (continued):
Sharing a sentence is not in itself a finding about the gene and the disease.
Listeria infection (1 paper, 2022). "Together, these results demonstrate that Kmt2d regulates activation-induced CD8+ T cell survival and death in vivo during Listeria infection." (PMID 36741385, 2022).
liver fibrosis (1 paper, 2025). "Further research revealed that exercise training improved liver fibrosis in NASH mice by downregulating lysine methyltransferase 2D (KMT2D)-mediated IDI1 histone methylation, which inhibits apoptosis." (PMID 40182630, 2025).
lymphoid neoplasm (1 paper, 2016). A neoplasm composed of a lymphocytic cell population which is usually malignant (clonal) by molecular genetic and/or immunophenotypic analysis. "In addition, in the current study, we report for the first time recurrent mutations (5-10%) in CMML in the genes CREBBP, KMT2D and UMODL1, which have been previously reported in lymphoid neoplasms or solid tumors." (PMID 27486981, 2016).
lymphopenia (1 paper, 2024). Reduction in the number of lymphocytes. "Thymic egress is supported by our observation of T-cell lymphopenia and by the near-complete absence of KMT2D locus recombined cells in the peripheral T-cells of Kmt2d KO (LckMar-Cre+Kmt2d-SET-fl/fl) mice." (PMID 38765012, 2024).
Macular dystrophy (1 paper, 2024). Macular dystrophy is a nonspecific term for retinal degeneration, generally confined to the macula, usually presumed of genetic origin. "We report two unrelated female patients with macular dystrophies and de novo nonsense variants in KMT2D: a known c.11119C>T; p.(Arg3707ter) pathogenic variant and a novel c.14843C>G; p.(Ser4948ter) variant." (PMID 38206414, 2024).
mantle cell lymphoma (1 paper, 2024). Mantle cell lymphoma is a rare form of malignant non-Hodgkin lymphoma affecting B lymphocytes in the lymph nodes in a region called the ``mantle zone''. "KMT2D mutations are associated with poor prognosis in patients with DLBCL, mantle cell lymphoma, and T cell lymphoblastic lymphoma." (PMID 39025450, 2024).
metastasis (1 paper, 2023). The spread or migration of cancer cells from one part of the body (where they first appeared) to another.
myocardial infarction (1 paper, 2023). Gross necrosis of the myocardium, as a result of interruption of the blood supply to the area, as in coronary thrombosis. "Our previous studies demonstrated that cardiomyocyte-specific KMT2D knockout mice exhibited larger infarct size after myocardial infarction surgery with reduced expression of functional genes." (PMID 36947365, 2023).
nephrocalcinosis (1 paper, 2025). Nephrocalcinosis is a disorder that occurs when too much calcium is deposited in the kidneys. "A prior single-center cohort study reported that 3 of 32 patients (9.4%) with nephrolithiasis/nephrocalcinosis had KS caused by KMT2D mutations." (PMID 40437108, 2025). "In our location-based analysis of pLoF variants in KMT2D, nephrocalcinosis and/or nephrolithiasis were more prevalent in patients with variants located towards the C-terminus." (PMID 40437108, 2025). "In the location-based analysis of patients with pLoF variants in KMT2D, the C-terminus group exhibited a significantly higher prevalence of nephrolithiasis and/or nephrocalcinosis compared to the non-C-terminus group." (PMID 40437108, 2025).
Obesity (1 paper, 2021). Accumulation of substantial excess body fat. "Heterozygous Kmt2d+/− mice demonstrated improved obesity, lipid accumulation, glucose tolerance, and insulin sensitivity." (PMID 34867780, 2021).
oral cavity cancer (1 paper, 2021). A primary or metastatic malignant neoplasm involving the oral cavity. "In a study similar to ours, where WES was performed in primary tumours of 51 HPV+ OPSCC, of which 35 did not recur, and 16 recurred, and in 33 primaries of HPV− oral cavity cancers and OPSCC, KMT2D was found to be the most commonly mutated gene in both primary (14%) and recurrent (42%) HPV+ OPSCC." (PMID 35008243, 2021).
oral squamous cell carcinoma (1 paper, 2022). "Specifically, the histone lysine methyltransferase KMT2D is among the most frequently mutated genes in oral squamous cell carcinoma (OSCC)." (PMID 35477537, 2022).
orofacial cleft (1 paper, 2022). A disorder of facial skeleton that is characterized by cleft lip and/or cleft palate that result in feeding, speech and hearing problems caused by failures during development. "Mouse knockouts of Acan,Dhrs3, Kmt2d, Recql4, Shh and Tp63 showed orofacial cleft phenotypes." (PMID 35817949, 2022).
osteoporosis (1 paper, 2024). A condition of reduced bone mass, with decreased cortical thickness and a decrease in the number and size of the trabeculae of cancellous bone (but normal chemical composition), resulting in increased fracture incidence. "The Venn plot found that hsa-miR-204-5p was associated with osteoporosis and had the highest confidence in binding to KMT2D." (PMID 39867575, 2024). "Subsequently, we predicted the upstream miRNA of KMT2D gene and analyzed the mechanism of KMT2D in osteoporosis, the potential prognostic value and its immune invasion of KMT2D in pan-cancer." (PMID 39867575, 2024). "To identify potential targets for treating osteoporosis, we have verified the ferroptosis-related KMT2D gene and MYCN gene, both of which are drivers of ferroptosis." (PMID 39867575, 2024). "The independent dataset validated that the expression level of KMT2D was significantly upregulated in osteoporosis samples." (PMID 39867575, 2024). "All results suggest that KMT2D may be involved in the regulatory process of cellular senescence and osteoporosis." (PMID 39867575, 2024). "Our study found that KMT2D is significantly upregulated in patients with osteoporosis and AML, indicating that KMT2D may be a potential therapeutic target for patients with osteoporosis and AML." (PMID 39867575, 2024).
ovarian carcinoma (1 paper, 2017). A malignant neoplasm originating from the surface ovarian epithelium. "Finally, variants in the genes ROS1, NOTCH1, ALK, KMT2D, and SPOP have to our knowledge not previously been reported in ovarian cancer." (PMID 28611940, 2017).
pancreatic ductal adenocarcinoma (1 paper, 2024). An infiltrating adenocarcinoma that arises from the epithelial cells of the pancreas. "Combining analyses of RNA‐seq and ChIP‐seq data, the authors further identify killin (KLLN) as a transcriptional target of KMT2D and EBF2 in pancreatic ductal adenocarcinoma (PDAC) cells." (PMID 38015024, 2024).
parathyroid carcinoma (1 paper, 2023). "Other mutations in KMT2D, KRAS (in-frame deletion), and FRAT2 (FRAT regulator of WNT signaling pathway 2) are potentially associated with the oncogenesis of parathyroid carcinoma; however, the evidence remains limited." (PMID 37121965, 2023).
pediatric cancers (1 paper, 2020). "Moreover, heterozygous germline inactivating mutations in KMT2D have been linked to several cancers, and decreased germline activity of KMT2D was found in various pediatric cancers." (PMID 33302406, 2020).
plasma cell neoplasm (1 paper, 2025). A clonal proliferation of immunoglobulin-secreting plasma cells. "These somatic alterations have been implicated in various processes central to plasma cell neoplasms, from chromatin remodeling (ARID1A, KMT2D, and BCL7A) to oncogenic signaling (PTPN11, NUP214)." (PMID 41378284, 2025).
polycystic kidney (1 paper, 2025). "In this study, we observed that the ultrasound phenotypes of a fetus with HNF1B mutation included hyperechoic kidney and polycystic kidney, whereas the ultrasound phenotypes of the fetus with NPHP3 and KMT2D gene mutations included hyperechoic kidney and abnormal nervous system structure." (PMID 40909434, 2025).
pulmonary disorders (1 paper, 2023). "Recent evidence has shown that KMT2D mutations are associated with pediatric pulmonary disorders." (PMID 37641008, 2023).
renal agenesis (1 paper, 2022). Renal agenesis (RA) is a form of renal tract malformation characterized by the complete absence of development of one or both kidneys (unilateral RA or bilateral RA respectively), accompanied by absent ureter(s). "KMT2D gene variants are also related to CAKUT and renal agenesis." (PMID 35361250, 2022).
renal cell carcinoma (1 paper, 2025). "In renal cell carcinoma (RCC), for example, a panel of mRNA markers (CUL9, KMT2D, PBRM1, PREX2, and SETD2) has been identified as a highly accurate classifier, distinguishing RCC from benign renal masses with an AUC of 0.83." (PMID 40149276, 2025).
schwannoma (1 paper, 2020). A benign, usually encapsulated slow growing tumor composed of Schwann cells. "Particularly, ATM, accounting for 33% of the samples, was the most frequently mutated cancer-related gene in schwannoma, followed by CHD4, FAT1, KMT2D, MED12, NF2, and SUFU (>20%)." (PMID 33193598, 2020).
sclerosing pneumocytoma (1 paper, 2022). "Mutations in other tumor-related genes were also identified in the sclerosing pneumocytoma, like PTEN, BRAF V600E, BLM, KMT2D, but with relatively smaller incidence than AKT1 and β-catenin." (PMID 35490241, 2022).
Sertoli Cell-Only Syndrome (1 paper, 2021). A type of male infertility in which no germ cells are visible in any of the biopsied SEMINIFEROUS TUBULES (type I) or in which germ cells are present in a minority of tubules (type II). "It has been reported that DNA methylation deficiency caused by deficiency of methyltransferase KMT2D is impaired by ROS and is implicated in spermatogenesis, Sertoli cell only syndrome, and the incidence of testicular cancer." (PMID 33488282, 2021).
Smith-Magenis syndrome (1 paper, 2026). Smith-Magenis syndrome (SMS) is a complex genetic disorder characterized by variable intellectual deficit, sleep disturbance, craniofacial and skeletal anomalies, psychiatric disorders, and speech and motor delay. "In addition, the closest established episignatures resembling NOTCH1 were found to be KMT2D-related as well as Smith-Magenis syndrome, which is associated with impairment of RAI1." (PMID 41501857, 2026).
T-cell neoplasm (1 paper, 2020). "In addition to epigenetic modifiers implicated in all subtypes of T-cell neoplasm (TET2, DNMT3A, KMT2D, KMT2C, SETD2), recurrent mutations of the FAT1 tumor suppressor gene were for the first time recorded in 39% of cases." (PMID 31028364, 2020).
thymic carcinoma (1 paper, 2023). Thymic carcinoma (TC) is a type of thymic epithelial neoplasm characterized by a high malignant potential.
tongue tumors (1 paper, 2024). "Decreased KMT2D protein levels in Kmt2d-HT mice tongue tumors were confirmed by immunohistochemistry (IHC)." (PMID 39117659, 2024).
ulcerative colitis (1 paper, 2021). An inflammatory bowel disease involving the mucosal surface of the large intestine and rectum. "According to these data, mutations in KMT2D gene have been identified in ulcerative colitis-associated colorectal neoplasia." (PMID 33602320, 2021).
Waldenström's Macroglobulinemia (1 paper, 2024). "Despite recurrent and activating mutations, including MYD88, CXCR4, ARID1A, KMT2D, and CD79B were identified, the genetic basis for Waldenström's Macroglobulinemia (WM) and the risk of progression of IgM MGUS to WM remain to be fully elucidated." (PMID 39711167, 2024).
tumor (219 papers, 2013 to 2025). "Mechanistic analysis revealed that KMT2D deficiency potentially remodeled the tumor immune microenvironment through epigenetic reprogramming, characterized by enhanced CD8+ T-cell infiltration." (PMID 40895533, 2025). "A specific analysis of known cancer driver genes revealed NRAS as the most frequently mutated gene (6/8 tumor populations), followed by KMT2D (5/8 tumor populations) and COL5A1 (5/8 tumor populations)." (PMID 40004220, 2025). "Two polyps with defects in WNT signaling also showed KMT2D mutations p.E3216* and p.Q3312Rfs*18 which have been reported in tumors with high tumor MB that often respond favorably to immunotherapy." (PMID 40757636, 2025). "PIK3CA encodes a subunit of phosphatidylinositol 3-kinase (PI3K), which is essential to cell survival, while KMT2D, which encodes a histone modulator, has both tumor suppressor and tumor promoter properties." (PMID 41301029, 2025). "Due to the high mutational frequency of the KMT2D gene in their review, they assert the strong association of the gene with tumor progression and its potential to serve as a biomarker for predicting immunotherapy response." (PMID 41590495, 2025). "The LLPS microenvironment driven by the two LCDs of KMT2D facilitates H3K4 histone monomethylation transcription as well as the expression of the tumor-associated TFs LIFR and KLF4, promoting tumor progression." (PMID 40642070, 2025). "Prior research identifies KMT2D as a tumor suppressor, where loss-of-function mutations impair transcriptional regulation and promote oncogenesis." (PMID 41590495, 2025). "These suggest the tumor-suppressive role of KMT2D, supported by its association with a gene signature resembling the aggressive Moffitt basal-like subtype and indicating a poorer prognosis compared to the classical subtype." (PMID 38791111, 2024). "We applied our method to map the genetic networks of KMT2D, a frequently mutated tumour suppressor gene across cancer types." (PMID 39578878, 2024). "Mutations in KMT2D often result in a loss of function, suggesting its role as a tumor suppressor in various tissues." (PMID 39620228, 2024). "Here, we computationally map genetic networks of KMT2D, a tumour suppressor gene frequently mutated in several cancer types." (PMID 39578878, 2024). "Gene ontology (GO) analyses of the RNA-seq data revealed that the upregulated pathways in KMT2B and KMT2D KD BCCs were associated with tumor progression, e.g., inflammatory cues and cell migration." (PMID 38347590, 2024). "Further exploratory analysis using gene expression profiles of SCLC patients indicated that KMT2D mutations affect various immune cell populations within the tumor microenvironment, including CD8+ T cells, Th1 cells, and M2 macrophages." (PMID 39278918, 2024). "Through modulation of glucose and lipid metabolism and cell plasticity, low expression levels of KMT2D cause proliferation, the epithelial–mesenchymal transition, and tumor progression in PDAC." (PMID 38791111, 2024). "We find that the glycolytic inhibitor 2-DG preferentially impedes the tumor growth of KMT2D-deficient HNSCC." (PMID 39117659, 2024). "Collectively, the results showed that KMT2B and KMT2D KD changed the transcriptional landscape of BCCs; particularly, upregulating genes associated with tumor growth." (PMID 38347590, 2024). "In human DLBCL and FL, KMT2D aberrations are typically loss of function events, either leading to truncations or deleterious missense mutations within the SET domain, indicating that KMT2D acts as a tumor suppressor gene." (PMID 38124747, 2023).
tumor (continued). "KMT2D is a tumour suppressor gene encoding histone-lysine N-methyltransferase 2D, which is vital for embryonic development, and it is widely expressed in adult tissue." (PMID 37559138, 2023). "This frequency is even higher, up to 90%, in adult follicular lymphoma and mutations in KMT2D are supposed to be driver events in various tumor types." (PMID 35856126, 2023). "In this study, U2AF1, DNMT3A, SF3B1, and EZH2 in the secondary tumor group was higher than that in the tumor‐free group, while the mutation rate of ASXL1, TET2, and KMT2D was higher in the tumor‐free group." (PMID 36727544, 2023). "Loss-of-function mutations in Lysine Methyltransferase 2D (KMT2D) were found to potentiate anti-PD1 checkpoint immunotherapy by enhancing immune infiltration in the tumor microenvironment." (PMID 38162677, 2023). "Nonetheless, KMT2D deficiency has been shown to increase tumor sensitivity to various types of immune checkpoint inhibitors." (PMID 37512096, 2023). "KMT2D is a broadly expressed histone methyltransferase that is believed to function as a tumor suppressor and is frequently mutated in a wide variety of cancers." (PMID 36712323, 2022). "By encoding histone methyltransferase, KMT2D is critically involved in the epigenetic and transcriptional regulation of certain tumor‐associated genes." (PMID 35486034, 2022). "It has been shown that KMT2D mutations are associated with increased tumour size and unfavorable prognosis in patients with EC." (PMID 35281814, 2022). "Although KMT2D is heavily associated with the methylation level of histones and the regulation of many transcription factors that affect tumor progression, the functions of many of its structures remain poorly studied." (PMID 34758724, 2021). "We also demonstrated that lung-specific loss of Kmt2d significantly promoted K-RasG12D–driven lung tumorigenesis by upregulating tumor-promoting programs." (PMID 34194626, 2021). "Tumor suppressor genes Kmt2d and Dusp4 showed similar loss of interactivity of their promoters with putative H3K27Ac rich loci in Smc3/Bcl6 tumors." (PMID 34621263, 2021). "It has been further observed that H3K4me1-marked enhancer reprogramming by KMT2D loss is associated with a drastic alteration of the central metabolic pathways in the tumor cells." (PMID 34575678, 2021). "KMT2D functions as a tumour suppressor and KMT2D deficiency impedes B-cell differentiation and B-cell signalling pathways." (PMID 34638403, 2021). "Because KMT2D harbors truncating mutations in many types of cancer, KMT2D have been considered a tumor-suppressor in such instances." (PMID 34194626, 2021). "KMT2D has emerged as a frequently mutated gene in about 8.5% of all cancers and has been proposed to play either a tumor suppressor or oncogenic role, depending on cancer type." (PMID 32878339, 2020). "The resulting frequencies of some mutated genes such as NOTCH1 (33.3%), PIK3CA (25.6%), and KMT2D (30.8%) were higher compared to that in previously single-tumor studies." (PMID 30975989, 2019). "This truncating mutation was located prior to the enzymatic SET domain, similar to those truncating KMT2D mutations identified in our tumor cohorts." (PMID 29950560, 2018). "Somatic mutations of the LUSC2 tumor were also found in a number of novel driver genes such as Myh9, Kmt2d and Keap1." (PMID 29484121, 2018). "Loss-of-function Kmt2d mutations detected in one mouse tumor was previously reported in 30 of 366 human MBs." (PMID 29029386, 2017). "Mutations in KMT2D identified thus far point to its loss-of-function in pathogenesis and suggest its role as a tumor suppressor in various tissues." (PMID 24240169, 2013). "Besides, the mutations of FOXO1 or KMT2D are demonstrated closely related to tumor microenvironment." (PMID 41372946, 2025).